MPI (mannose phosphate isomerase)
Description:
Isomerase that catalyzes the interconversion of fructose-6-P and mannose-6-P and has a critical role in the supply of D-mannose derivatives required for many eukaryotic glycosylation reactions.
Synonyms: PMI; PMI1; CDG1B
Tractability: Small molecule: a high-quality ligand is known; it belongs to a druggable protein family. Antibody: the Human Protein Atlas places it where antibodies can reach. PROTAC: ubiquitination databases record sites on it; its protein half-life has been measured; a small molecule that binds it is known.
Target class: Isomerase; Enzyme
Chemical probes: ML089, ML096
Gene: Protein-coding gene on chromosome 15 (74,890,005 to 74,902,219, forward strand). Ensembl gene ENSG00000178802.
Subcellular location: Cytoplasm
Subcellular location (Human Protein Atlas): Cytosol; Plasma membrane
Pathways (Reactome):
Disease: Defective MPI causes MPI-CDG
Metabolism of proteins: Synthesis of GDP-mannose
Gene Ontology:
Molecular function: mannose-6-phosphate isomerase activity; zinc ion binding
Biological process: GDP-mannose biosynthetic process; mannose to fructose-6-phosphate catabolic process; carbohydrate metabolic process
Cellular component: extracellular exosome; cytoplasm; cytosol
Genetic constraint (gnomAD): Loss-of-function variants: 34 observed, 43.51 expected, observed/expected ratio (o/e) 0.78, 90% interval 0.59 to 1.04. The upper end of that interval is the gene's LOEUF score, 1.04, which puts it in group 4 of 6, group 1 being the genes least tolerant of losing a copy. Missense variants: 514 observed, 552.1 expected, observed/expected ratio (o/e) 0.93, 90% interval 0.87 to 1. Synonymous variants: 187 observed, 220.45 expected, observed/expected ratio (o/e) 0.85, 90% interval 0.75 to 0.96.
Gene-disease validity (ClinGen):
ClinGen rates the evidence that MPI causes each of these diseases.
MPI-congenital disorder of glycosylation (autosomal recessive): Definitive.
Homologues: Orthologues: chimpanzee MPI (99% identical), macaque MPI (98% identical), pig MPI (90% identical), dog MPI (88% identical), guinea pig MPI (86% identical), rat Mpi (86% identical), mouse Mpi (85% identical), rabbit MPI (82% identical), zebrafish mpi (63% identical), tropical clawed frog mpi (63% identical), Caenorhabditis elegans ZK632.4 (39% identical), Caenorhabditis elegans C05C8.7 (36% identical), and 1 more.
Diseases named in the same sentence as MPI in open-access papers:
MPI is named in the same sentence as 36 diseases in open-access papers, as found by Europe PMC text mining. Sharing a sentence is not in itself a finding about the gene and the disease. The quoted sentences say what the papers report.
Hepatic fibrosis (4 papers, 2015 to 2022). The presence of excessive fibrous connective tissue in the liver. "Besides fibrogenic gene overexpression, mutations in mannose phosphate isomerase (mpi) present in hepatocytes also promotes hepatic fibrosis." (PMID 34203824, 2021). "Partial loss of MPI function in humans leads to a congenital disorder of glycosylation (CDG; MPI-CDG) characterized by hepatic fibrosis, biliary malformations, protein-losing enteropathy, and coagulopathy." (PMID 28644127, 2017).
congenital disorder of glycosylation (3 papers, 2017 to 2021). Congenital disorder of glycosylation (CDG) is a fast growing group of inborn errors of metabolism characterized by defective activity of enzymes that participate in glycosylation (modification of proteins and other macromolecules by adding and processing of oligosaccharide side chains). "The mannose phosphate isomerase-congenital disorder of glycosylation (MPI-CDG) is caused by phosphomannose isomerase deficiency." (PMID 32963965, 2020).
glioma (2 papers, 2014 to 2025). A benign or malignant brain and spinal cord tumor that arises from glial cells (astrocytes, oligodendrocytes, ependymal cells). "To determine the functional importance of MPI expression for RTK signaling in gliomas, we used lentiviral transduction to generate U-251 cells expressing either MPI-shRNA knockdown or a scramble shRNA sequence." (PMID 25314669, 2014). "The results of siRNA knockdown of MPI in SKMG-3 cells therefore provide further experimental evidence for the role of MPI in regulating FGF family receptor signaling in glioma." (PMID 25314669, 2014). "The result of MPI siRNA knockdown on cell migration was also investigated in the SKMG-3 glioma cell line, and like the U-251 cells, we found impaired migration after MPI knockdown with partial rescue by FGF1." (PMID 25314669, 2014). "In addition to a blockade of cellular migration, MPI knockdown also significantly reduced glioma cell clonogenic survival following ionizing radiation." (PMID 25314669, 2014). "In agreement with this hypothesis, we now show that MPI deficiency interferes with FGFR activation and glioma radiation responses, and identifies MPI as a potential NLG enzymatic target for cancer therapy." (PMID 25314669, 2014).
asthma (1 paper, 2020). "Interestingly, 4 genes of MPI, DECR2, LNPEP, and TTC19 are newly reported to be involved in severe asthma risk." (PMID 33066754, 2020).
esophageal cancer (1 paper, 2022). A primary or metastatic malignant neoplasm involving the esophagus. "The expression of mannose phosphate isomerase (MPI) in human esophageal cancer cell lines were detected by Western blot." (PMID 35201482, 2022).
hyperinsulinism (1 paper, 2023). Abnormally high levels of insulin in the blood. "The entities reported to be associated with hyperinsulinism are PMM2-CDG (CDG1a), MPI-CDG (CDG1b), ALG3-CDG (CDG1d), and PGM1-CDG (CDG1t) (reviewed by 97, 98)." (PMID 37065762, 2023).
liver disease (1 paper, 2021). "The authors classified CDG based on liver involvement into two main groups: one with predominant/isolated liver involvement (MPI-CDG, CCDC115-CDG, TMEM199-CDG, ATP6AP1-CDG) and the other associated with liver disease (PMM2-CDG, ALG1-CDG, ALG3-CDG, ALG8-CDG, ALG9-CDG, PGM1-CDG)." (PMID 34291020, 2021).
lung carcinoma (1 paper, 2024). "Although MPI’s direct link to lung cancer requires further elucidation, its metabolic functions hint at a role in cancer metabolism." (PMID 39529882, 2024).
malignant glioma (1 paper, 2014). A grade III or grade IV glioma arising from the central nervous system. "Loss of FGFR signaling after MPI knockdown also revealed a migration defective phenotype as well as sensitivity to ionizing radiation in vitro, suggesting MPI is a potential therapeutic target for malignant glioma." (PMID 25314669, 2014). "Loss of MPI activity reduced phosphorylation of FGFR family receptors in U-251 and SKMG-3 malignant glioma cell lines and also resulted in significant decreases in FRS2, Akt, and MAPK signaling." (PMID 25314669, 2014).
melanoma (1 paper, 2024). A malignant, usually aggressive tumor composed of atypical, neoplastic melanocytes. "Therefore, as reported in this study, the proteomic/degradomicmapping of mannose downstream effects due to the metabolic rewiringcaused by the functional status of the MPI enzyme could lead to theidentification of specific molecular players from affected signalingcircuits in melanoma." (PMID 39420811, 2024).
pancreatic cancer (1 paper, 2019). "A recent study showed that high mannose treatment leads to inhibition of tumor growth in mannose phosphate isomerase (MPI)-low pancreatic cancer cells." (PMID 31569510, 2019).
Thrombocytopenia (1 paper, 2025). A reduction in the number of circulating thrombocytes. "Notably, thrombocytopenia has also been described in various other types of CDG, including ALG1-, ALG8-, GALE-, GNE-, MPI-, PMM2-, and B4GALT1-CDG." (PMID 40613041, 2025).
tumor (8 papers, 2018 to 2024). "Under the condition of less energy supply in tumor cells with high expression of MPI, mannose-6-phosphate was converted to mannose-6-phosphate and contributes to glucose metabolism." (PMID 35201482, 2022). "Among tumor cells, KYS450 was associated with the lowest expression of MPI, whereas KYSE70 was correlated with the highest expression of MPI; meanwhile, SHEE cell line was also associated with low MPI expression." (PMID 35201482, 2022). "We have recently demonstrated that MPI, apical enzyme in the mannose catabolic pathway, opposes the anti-tumor effects of such sugar, by preventing mannose-6-phosphate accumulation in cancer cells." (PMID 33311467, 2020). "However,we demonstrated that mannose, the epimer of glucose, provides opportunitiesto treat neoplasia, in which the MPI gene has low expression." (PMID 39420811, 2024).
cancer (7 papers, 2014 to 2024). A tumor composed of atypical neoplastic, often pleomorphic cells that invade other tissues. "Suppression of MPI expression potentiates the anti-proliferative effects of mannose on cancer cells." (PMID 33311467, 2020). "Thus, studies have considered mannose pathway enzymes like MPI in cancer to reveal an important role for balanced fructose and mannose metabolism." (PMID 34436420, 2021). "An examination of human cancer cell lines that express varying levels of MPI clearly indicated that the antiproliferative effect of mannose is largely dependent on the expression levels of MPI, while mannose-driven genomic instability is a unique phenotype observed in the absence of MPI." (PMID 37461317, 2023). "In this study, we describe a previously unappreciated function of MPI as a glycolytic regulator, separate from its effects on protein N-glycosylation, and its important contribution to the metabolic regulation driving cellular proliferation in embryonic development and cancer." (PMID 28644127, 2017). "To establish MPI-KO human cancer cells using the CRISPR–Cas9 system, we exploited the mannose auxotrophy and sensitivity observed in MPI-KO mouse embryonic fibroblasts (MPI-KO MEFs)." (PMID 37461317, 2023).
MPI also shares sentences with these, for which no sentence is quoted: Protein-losing enteropathy (4 papers); Hypoglycemia (3); colon cancer (2); Allergy (1); breast carcinoma (1); copper metabolism disorder (1); experimental autoimmune encephalomyelitis (1); fructose intolerance (1); glycogenosis (1); head and neck tumour (1); Hypertension (1); Hypoalbuminemia (1); infection (1); leukemia (1); leukocyte adhesion deficiency (1); malaria (1); pericarditis (1); Renal cyst (1); renal failure (1); steatosis (1); Stroke (1); type 2 diabetes (1).